TRPM8 (transient receptor potential cation channel subfamily M member 8)
Diseases named in the same sentence as TRPM8 in open-access papers (continued):
Sharing a sentence is not in itself a finding about the gene and the disease.
cancer (continued). "This article focuses on the transient receptor potential melastatin-subfamily member 8 (TRPM8) ion channel in cancers, with an emphasis on its roles in proliferation, survival, and invasion." (PMID 26512697, 2015). "The role of TRPM8 in cancer cell proliferation was determined by genetic silencing of TRPM8 expression, ectopic expression of TRPM8, and chemical activation or inhibition of TRPM8 channel activity." (PMID 26512697, 2015). "The goal of this article is to provide a critical review of the transient receptor potential melastatin-subfamily member 8 (TRPM8) in cancers, with an emphasis on its roles in cellular proliferation, survival, and invasion." (PMID 26512697, 2015). "Taken together, the data from those experiments using different types of cancer cells support an important role of TRPM8 in cellular proliferation that is dependent on the cellular, and probably the molecular, context." (PMID 26512697, 2015). "I hope this article will help stimulate research efforts and collaboration to understand the mechanistic roles of TRPM8 in malignant neoplasia, and to explore the potential of TRPM8 as a molecular biomarker and therapeutic target in precision oncology." (PMID 26512697, 2015). "The effects of modulating the expression and activity of TRPM8 channels in cancer cells migration and invasion have been investigated." (PMID 26512697, 2015). "The expression and roles of TRPM8 channels in various cancers will be described, with an emphasis on cancer type-dependent cellular proliferation, survival, and invasion." (PMID 26512697, 2015). "Translational research and clinical investigation of TRPM8 in malignant diseases will help exploit these ion channels as molecular biomarkers and therapeutic targets for developing precision cancer medicine." (PMID 26512697, 2015). "Evidence to date indicates that TRPM8 is expressed in a variety of solid tumors, and the functional roles of TRPM8 channels in cancer cells have been identified." (PMID 26512697, 2015). "Overall, our study highlights the importance of crosstalk between androgen-TRPM8-AR regulatory loop as it relates to cancer progression and cell proliferation." (PMID 25980497, 2015). "In pre-malignant pancreatic tissues and malignant neoplasms, TRPM8 is aberrantly expressed to variable extents." (PMID 24861976, 2014). "TRPM8 expression is strongly up-regulated in numerous cancers such as prostate, breast, colon, lung, pancreas and skin while it is dramatically reduced during metastasis in the androgen-independent prostate cancer." (PMID 24204345, 2013). "The focus of our basic research studies is to determine the signaling mechanisms that mediate the proliferative and migratory roles of TRPM7 and TRPM8 in pancreatic epithelia and cancer cells." (PMID 24278689, 2012). "TRPM8 protein can be present in the plasma membrane and in the endoplasmic reticulum of human prostate LNCaP cancer cell line." (PMID 20482834, 2010). "The calcium-permeable cation channel TRPM8 (melastatin-related transient receptor potential member 8) is over-expressed in several cancers." (PMID 20482834, 2010). "Functional TRPM8 channels have been clearly characterized in over-expression systems, in human cancer epithelial LNCaP cell line, and in primary culture of prostate epithelium cancer (PrPCa) cells." (PMID 20482834, 2010). "A growing number of studies demonstrate a close correlation between an overexpression of TRP channels particularly of the TRPV6 and TRPM8 families and the development of cancer." (PMID 18452628, 2008). "TRPM8 antagonism has also a potential role in suppressing cancer metastasization." (PMID 39940997, 2025). "In addition, TRPM8 expression is increased in various malignancies, making it a potential target or biomarker for cancer treatments." (PMID 41025355, 2025).
cancer (continued). "Additionally, several studies have explored the role of TRPM8 in cancer cell proliferation, migration, and apoptosis positioning this channel as a potential target for cancer therapy in combination with other treatment modalities." (PMID 40123199, 2025). "Targeting TRPM8 is important for treating diseases like peripheral neuropathies and cancer." (PMID 40123199, 2025). "The expression levels of TRPM-8 vary with stage of the cancer, which may affect the cancer’s response to the channel modulators." (PMID 40109334, 2025). "Importantly, cancer cell lines that represent the various tumor types consistently show that sub-lethal chemotherapy dosages combined with the TRPM8 agonist D-3263 have a synergistic lethal effect." (PMID 40405392, 2025). "The commonality between TRPM8 expression modulation and progression of many diverse types of cancer accounts for the increasing efforts to assess the effectiveness of using TRPM8 as a drug target for cancer therapy." (PMID 38339011, 2024). "Our results suggest that it may be possible to mitigate a major side effect of TRPM8 antagonists via route of administration, which may have a significant clinical impact on those undergoing treatment, as well as cancer survivors." (PMID 38794851, 2024). "Furthermore, the phosphorylation level of TRPM8, a TRPM member frequently undergoing post-translational modifications during cancer progression, is closely associated with PC progression." (PMID 39633507, 2024). "Therefore, TRPM8 is suggested as a molecular biomarker and therapeutic target for developing selective cancer treatment, since this channel is functional in etoposide-sensitive cancerous tumor types." (PMID 38339011, 2024). "Radiotherapy is currently used in treating several cancers, and it has been proposed that combining this therapy with TRPM8 modulation could be helpful in cancer therapy." (PMID 37033630, 2023). "However, considering the higher permeability of Ca2+ ions, most of the literature about the role of the TRPM8 channel in cancer is focused on Ca2+ signaling." (PMID 37033630, 2023). "Channel activity is related to diverse physiological processes, including proliferation and migration, and various reports have proposed TRPM8 channels as therapeutic targets for different cancer treatments, including bone, breast, skin, bladder, pancreas, prostate lung, and colon, among others." (PMID 37033630, 2023). "However, in some cancers, it has been reported that TRPM8 channel activation is enough to promote proliferation and migration in some tissues but decrease these processes in others." (PMID 37033630, 2023). "Expression of TRPM8 in diverse cell cancer lines and tissues from patients." (PMID 37033630, 2023). "The cell membrane channel, TRPM8, promotes tumor cell invasiveness in several cancers." (PMID 37240349, 2023). "TRPM8 is an established and already clinically pursued target in cancer therapy." (PMID 37240443, 2023). "In the next section, we will describe the reported functions of TRPM8 in diverse cancers." (PMID 37033630, 2023). "Considering these results, it could be interesting to carry on specific assays to evaluate the precise role of TRPM8 in response to paclitaxel in cancer prostate and other cancer cells." (PMID 37033630, 2023). "In addition to Ca2+, TRPM8 opening trigger the influx of Na+ and K+ ions which are essential for the control of diverse process involved in cancer progression as proliferation, cell volume regulation and apoptosis." (PMID 37033630, 2023). "Interestingly, it has been shown that TRPM8 channels also participate in physiological processes related to cancer, such as proliferation, survival, and invasion." (PMID 37033630, 2023). "TRPM8 is preferentially expressed in the plasma membrane in non-cancer cells." (PMID 37033630, 2023).
cancer (continued). "Interestingly, different studies reported an abnormal TRPM8 function in several forms of cancer, including prostate, pancreatic, breast, lung, and colon cancer; however, in some cases, the contribution to the pathology is still not entirely understood." (PMID 37388453, 2023). "There is increasing information about the role of TRPM8 modulation in cancer." (PMID 37033630, 2023). "Additionally, accumulating evidence indicates that TRPM8 is aberrantly upregulated in various cancers, and plays a promoting role in tumorigenesis and tumor progression." (PMID 35361751, 2022). "It is possible that TRPM8 may also be an effective immunotherapeutic target; however, its role in cancer needs to be more precisely defined." (PMID 35847920, 2022). "Different levels of expression may partly explain why TRPM8 appears to have different effects on prognosis in different cancers." (PMID 35847920, 2022). "To summarize, we used an integrated bioinformatic approach which found that high levels of TRPM8 may modulate immune infiltration and influence patient outcomes in many cancers." (PMID 35847920, 2022). "Nanocarriers loaded with TRPM8 agonists, such as WS–12, could thus be used in early cancer stages when TRPM8 is highly expressed in order to avoid tumor cell dissemination." (PMID 35743115, 2022). "The cellular context could also be involved in the definition of TRPM8′s role in cancer progression." (PMID 35743115, 2022). "Other Ca2+-toolkit proteins implicated in various cancers include calcineurin, SERCA pumps, SPCAs, PMCAs, the IP3R, RyRs, STIM proteins, T-Type VGCCs, TRPC1, TRPC3, TRPC6, TRP ion channel melastatin 2 (TRPM2), TRPM7 and TRPM8." (PMID 36046118, 2021). "For example, the identification and/or quantification of TRPM8 expression in each malignancy, and its evolution along tumor states, are essential because of the differential expression and role of TRPM8 channels among different cancer types." (PMID 34445208, 2021). "Transient receptor potential cation channel subfamily M member 8 (TRPM8) is a Ca2+ non-selective ion channel implicated in a variety of pathological conditions, including cancer, inflammatory and neuropathic pain." (PMID 33673444, 2021). "Several tumor growth progression and invasion capacity initial phases of different cancers (prostate, pancreas, colon, breast, lung, and skin), have also been connected with aberrant expression of TRPM8 channels, and suggest a potential protective role for TRPM8 antagonists." (PMID 33673444, 2021). "In BxPC-3 and MIAPaCa-2 cell lines, TRPM8 is crucial for the invasive ability of the cancer cells." (PMID 33925979, 2021). "Likewise, high expression of TRPM8 channels in cancer cells over normal cells was targeted for knockdown to show reductions in cancer cell migration." (PMID 33569087, 2020). "Similarly, TRPM8 is predominantly overexpressed in breast, pancreas, and prostate cancers where its expression correlates with increased cancer cell proliferation and invasion as well as reduced apoptosis and poor patient survival." (PMID 32575381, 2020). "A similar chemoresistance-promoting effect was observed for TRPM8 in several cancers." (PMID 32575381, 2020). "Thus, cumulative evidence is signaling TRPM8 channels as pivotal players in cold hypersensitivity, especially that provoked by cancer chemotherapy." (PMID 32843690, 2020). "Therefore, a better comprehension of TRPM8 function in thermosensation, pathogen infection, or cancer, and a deeper characterization of its expression in organs and cell types, will help to identify the relevant signaling pathways that can modulate TRPM8." (PMID 33147416, 2020). "Furthermore, the TRPM8 agonist WS12 encapsulated into lipid nanocapsules is able to impair cancer cell migration ability." (PMID 31801263, 2019). "TRPM8 is expressed or overexpressed in different cancer types (e.g., CRC, PCa, OSCC, and BC)." (PMID 31801263, 2019).
cancer (continued). "Currently, a variety of compounds are known to activate the TRPM8 channel and could be used as therapeutic agents to reduce cell migration in TRPM8-expressing cancers." (PMID 31138874, 2019). "The purpose of this study was to target cancer cell migration by acting on TRPM8 activity." (PMID 31138874, 2019). "TRPM8 is involved in cancer proliferation, invasion, and migration of LLC-2 lung cancer cells." (PMID 31801263, 2019). "Our data suggested that the involvement of TRPM8 channels on the oxidative stress-induced apoptosis in the cancer cells, because oxidative stress-induced apoptosis, which could be inhibited by TRPM8 blocker (ACA) treatment." (PMID 30858386, 2019). "There are numerous reports describing a role for TRPM8 in cancer cell migration and invasion." (PMID 29772843, 2018). "However, what is the physiological role of TRPM8 channels in the context of the prostate epithelium, and why is the protein so avidly degraded in cancer cells?" (PMID 28039451, 2017). "One of the plausible scenarios for the enhanced TRPM8 proteolysis could be a way for cancer cells to overcome consequences from the rapid Ca2+-uptake." (PMID 28039451, 2017). "For example, when TRPM8 channel localizes at the plasma membrane, it is mainly involved in cancer proliferation and migration by activation of various calcium dependent pathways, whereas ER ion channel localization has been shown to be involved in the balance between apoptosis and proliferation." (PMID 27409624, 2016). "TRPM8 is also aberrantly over-expressed in chronic pancreatitis, pancreatic intra-epithelial neoplasms, and intraductal papillary mucinous neoplasms, and various malignant tumors." (PMID 26512697, 2015). "How TRPM8 may contribute to cancer growth and metastasis as well as the clinical significance of TRPM8 in malignant tumors will be discussed." (PMID 26512697, 2015). "The clinical significance of TRPM8 channels in these malignant tumors remains to be demonstrated." (PMID 26512697, 2015). "However, results of the studies thus far suggest a cell-type dependent modulatory role of TRPM8 in tumor growth and progression through its regulatory effects on cancer cells proliferation." (PMID 26512697, 2015). "In the following section, the expression of TRPM8 in malignant neoplasms is described." (PMID 26512697, 2015). "Thus, the role of TRPM8 in cell survival and apoptosis appears to depend on the cancer cell types and how the TRPM8 expression/activity is modulated." (PMID 26512697, 2015). "Such discrepancy may depend on the type of cancer cells, their molecular phenotypes, and the interventions by which expression and activity of TRPM8 channels are modulated." (PMID 26512697, 2015). "Experimental data support an important role of TRPM8 channels in proliferation of cancer cells." (PMID 26512697, 2015). "The role of TRPM8 in survival of cancer cells has been examined in several types of tumors." (PMID 26512697, 2015). "The various roles of TRPM8 in cancer including proliferation, survival, and invasion are reviewed." (PMID 26512697, 2015). "Because up-regulation of TRPM8 expression has been observed in various types of cancer including prostate, breast, lung and colon, this cold thermorTRP has been proposed as a marker for cancer tracing." (PMID 25257900, 2014). "In addition, we will apply these findings to other cancer types which might help to classify iPolyP/TRPM8-sensitive/insensitive neoplasms." (PMID 40869063, 2025). "Furthermore, a multitarget cross‐activity may be beneficial in cancer patients treated with chemotherapy that develop a distal peripheral neuropathy, where a contribution of TRPM8, TRPV1, and TRPA1 channels has been reported." (PMID 40123199, 2025). "Furthermore, it is given a current perspective of TRPM8 regulating molecules that could be used in cancer therapy alone or combined with other known drugs or therapies." (PMID 37033630, 2023).
cancer (continued). "TRPM8, also defined as a “cold receptor”, as it is activated by chemical cooling agents (such as menthol), exhibits an increased expression in several cancer subtypes, including colon, breast, and prostate tumors, and it is considered to be a useful prognostic marker." (PMID 37892239, 2023). "Thus, the TRPM8 ion channel may regulate these processes in cancer cells by the enhancement of Ca2+-based intracellular signaling." (PMID 35847920, 2022). "Therefore, TRPM8 could be considered a useful target to block PCa growth by using TRPM8 antagonists, such as capsazepine, BCTC, cannabigerol, as well as TRPM8 agonists, including menthol and D–3263, depending on the cancer stage." (PMID 35743115, 2022). "Furthermore, neither the residues of TRPM8 involved in the interaction nor that of Rap1 are mutated in the cohort of patients of all types of cancer analyzed by us." (PMID 35565390, 2022). "Finally, in order to investigate the clinical relevance of TRPM8-Rap1A relative expression in the cancer types for which we studied protein-protein interaction, we used transcriptional data from TCGA and GTEx databases to perform differential expression analysis on both genes." (PMID 35565390, 2022). "In addition, TRPM8 expression could have a positive correlation with cancer development and metastasis formation." (PMID 33925979, 2021). "Similarly poorly understood are the mechanisms leading to upregulation of TRPM8 in cancer cells." (PMID 29221175, 2017). "Because of its potency and selectivity, together with the simplicity of its synthesis, compounds 41 and 45 represent new hits for TRPM8 modulation, which are now being further modified to discover new analogues with improved properties for prospective therapeutic application in pain and cancer." (PMID 28883526, 2017). "The mammalian transient receptor potential melastatin channel 8 (TRPM8), highly expressed in trigeminal and dorsal root ganglia, mediates the cooling sensation and plays an important role in the cold hypersensitivity characteristic of some types of neuropathic pain, as well as in cancer." (PMID 28883526, 2017). "However, experimental studies in a defined cellular and molecular context may help shed light on the mechanistic roles of TRPM8 in cancer biology." (PMID 26512697, 2015). "TRPM8 is highly expressed in prostate and other cancer cells, but, apart from its principal function in neurons as a detector of environmental cold, its physiological and pathological function in epithelia and cancer cells is unknown." (PMID 19778436, 2009). "TRPM8 was first described in prostate cancer and cloned as a molecule with high homology to a TRP-like channel; later on, its presence in several cancers, also including lung, gastric, liver, ovarian, melanoma, and breast, was assessed." (PMID 39940997, 2025). "Conversely, the TRPM8 agonists menthol and WS12 reduced cancer cell proliferation and migration ability." (PMID 39940997, 2025). "Thus, the design and validation of TRPM8 modulators are crucial for advancing our understanding on the contribution of TRPM8 to the etiology of neuropathic pain, inflammatory disorders, pruritus, and cancer and to select novel candidates for therapeutic development." (PMID 40123199, 2025). "More research is needed to decipher the complex modulatory effect of TRPM8 in the development and progress of diverse cancers, focusing on characterizing molecules highly selective for the TRPM8 channel that could be used in cancer treatment with minimal adverse effects." (PMID 37033630, 2023). "It is thus reasonable to believe that high levels of TRPM8 and TCAF2 co-expressions in PDAC correspond to cancer invasiveness and metastasis." (PMID 36012311, 2022). "TRPM8 is overexpressed at the plasma membrane and in the intracellular region of oral squamous cell carcinoma (SCC), promoting the proliferation of these cancer cells." (PMID 36844925, 2022).